EGF (epidermal growth factor)
Diseases named in the same sentence as EGF in open-access papers (continued):
Sharing a sentence is not in itself a finding about the gene and the disease.
prostate carcinoma (continued). "Because EGF was shown to induce AR transcription by upregulating TIF2 expression in prostate cancer cells, we then determined the levels of TIF2 expression in bladder cancer cell lines upon treatment with EGF, androgen and/or antiandrogen." (PMID 22922989, 2012). "Because previous studies showed ligand-independent activation of AR transcription by EGF in prostate cancer cells, we first assessed the effects of EGF and a specific EGFR inhibitor PD168393 on AR transactivation in bladder cancer lines." (PMID 22922989, 2012). "In Du145 prostate cancer cells, EGF produces pronounced cell migration and characteristics resembling epithelial-mesenchymal transition in a manner involving activation of Akt." (PMID 23133535, 2012). "It has also been shown that Src mediates EGF-induced AR tyrosine phosphorylation in prostate cancer cells, which leads to an increase in AR transcriptional activity." (PMID 22922989, 2012). "The AT2-receptor, through an interaction with its putative signaling partner MTUS1/ATIP (AT2-receptor interacting protein), inhibits the mitogenic effects of EGF in prostate cancer cell lines representing both early and late stage disease." (PMID 24213113, 2011). "EGF-SubA has also been shown to be efficacious in vivo, significantly inhibiting tumour growth in mouse xenograft models of human breast and prostate cancer." (PMID 20871837, 2010). "In DU145WT human prostate carcinoma cell lines, EGF increased the STAT3-targeted band; herein the antibody to human STAT3 eliminated DNA binding." (PMID 16804520, 2006). "The potential role of the epidermal growth factor (ErbB) family of receptors and their ligands in regulating AR activity during prostate cancer progression is currently a focus of intense investigation." (PMID 15583694, 2005). "Such crosstalk interactions among different signal transduction pathways have been documented recently between IL-6 and EGF pathways in prostate cancer cells." (PMID 12671705, 2003). "With progression, prostate cancer cells switch from epidermal growth factor (EGF) to transforming growth factor α (TGF-α) synthesis, which contributes to autocrine growth and unrestrained proliferation." (PMID 10360641, 1999). "Therefore, EGF has overall less survival ability in prostate cancer but is high in BRCA compared to CCL18." (PMID 40692603, 2025). "Indeed, REDLK deletion resulted in a strong decrease in cytotoxicity of the targeted toxin in prostate cancer cells compared to the parental targeted toxin EGF-PE24mut." (PMID 37859824, 2023). "Moreover, berberine-down-regulated EGFR activation stimulated by EGF led to a reduction in phosphorylated EGFR expression in prostate cancer PC-3 cells, which supported our findings." (PMID 36770659, 2023). "Moreover, Kuo and colleagues showed that PGG treatment decreased the MMP-9 activity in prostate cancer cells and inhibited bone metastasis by blocking the EGF-induced JNK1/2 and NF-κB signaling pathways." (PMID 37375411, 2023). "Using the WGS data, we assessed the presence of variants and/or mutations in several genes that are known to be frequently mutated in prostate cancer (BRCA1, BRCA2, RB, PTEN, CDK12, PI3K, ADP-ribose, PIK3GA, PIK3CB and PIK3R1, AKT, CYP17, IGF 1, EGF, and BCL2)." (PMID 36643868, 2022). "Moreover, EGF can induce Twist1 expression and prostate cancer cell invasion through a ROS/STAT3/HIF-1α signaling cascade." (PMID 36669020, 2022). "EGF and EGF receptor (EGFR) are aberrantly expressed in both androgen-independent and metastatic prostate cancers, with high EMT-related features, and are strongly associated with an aggressive phenotype, a poor clinical prognosis, a high Gleason score, and a reduced survival rate." (PMID 36669020, 2022). "The previous study has figured out Lycorine's anti-proliferative and anti-migratory properties for prostate cancer in many prostate cancer cell lines, which may prevent EGF-induced JAK/STAT signaling via dependent on STAT expression." (PMID 36046655, 2022).
prostate carcinoma (continued). "It will be intriguing to investigate whether we can target δ-catenin to block EGF signaling in prostate cancer patients." (PMID 34069970, 2021). "Mechanistically, TGFα, a member of the epidermal growth factor (EGF) family, was shown to bind to the EGFR leading to a significant AKT activation in the late-stage prostate cancer cells, whereas stimulation of early-stage prostate cancer cells with EGF diminishes AKT activation." (PMID 34064589, 2021). "EGF is one of the important upstream signals in prostate cancer." (PMID 34069970, 2021). "Moreover, we found that EGF was one of the upstream ligands for regulating AKT/δ-catenin signaling in prostate cancer." (PMID 34069970, 2021). "Notably, the results showed that EGF can significantly rescue HE4 mediated the prostate cancer metastasis suppression, which is consistent with the effect of EGFR overexpressed." (PMID 32678075, 2020). "We cultured human PC-3 prostate cancer cells in growth factor defined (epidermal growth factor [EGF] and fibroblast growth factor [FGF]-2) serum-free medium for the enrichment of PCSCs and detected the stem cell markers including Notch-1, Oct-4, and Nanog in PCSCs and parental cells." (PMID 32586404, 2020). "However, knockdown and knockout of endogenous Gαi2 in prostate cancer cells induced an attenuation of EGF-dependent cell migration and invasion." (PMID 32575572, 2020). "However, in a model of EGF-induced EMT in prostate cancer cells, HSP27 was required for modulation of the EGF/Akt/β-catenin/Slug signaling pathway." (PMID 32268506, 2020). "Interestingly, the thymosin beta 15B (TMSB15B) is involved in epidermal growth factor-induced migration of prostate cancer cells." (PMID 30626092, 2019). "Multiple pathways have been shown to induce NED in prostate cancer cells in vitro, including androgen deprivation, interleukin-6 (IL-6) treatment, Wnt pathway activation, EGF signaling pathways, activation of the cyclic adenosine 3′, 5′-monophosphate (cAMP) signaling pathway, or ionizing radiation." (PMID 29721191, 2018). "For instance, knockdown of EGF could inhibit prostate cancer cell EMT by promoting β-catenin ubiquitination." (PMID 30249289, 2018). "Hsp27 may act as an inducer of EMT activated by EGF; in addition, in prostate cancer it plays a crucial role in controlling both E-cadherin expression modulation mediated by β-catenin and EMT transcriptional regulation." (PMID 28430640, 2017). "Interestingly, EGF can interact with Src tyrosine kinase pathway in the induction of EMT in TMPRSS2-ERG positive prostate cancers." (PMID 28430640, 2017). "Its increased expression correlates with prostate cancer progression to castration-resistant disease and it is essential for EGF-promoted cell migration and invasion, as well as for EMT markers expression, AKT and GSK3β phosphorylation induced by EGF, and consequently for β-catenin stabilization." (PMID 28430640, 2017). "REPS2 is found to be involved in EGF signaling pathway in prostate cancer." (PMID 27120794, 2016). "Also, it seems that EGF plays an important role in stimulation of invasiveness of prostate cancer by promoting chemomigration of tumorous cells." (PMID 26042506, 2015). "The preferential regulation of the EGF pathway by cycling hypoxia was also observed in GSEA, which showed a predominance of gene sets associated with EGF in cycling samples subjected to hypoxia, especially in ovarian and prostate cancer cells." (PMID 25122487, 2014). "Moreover, AZA1-treatment also resulted in Rac1 and Cdc42 inhibition associated with suppression of cell proliferation in EGF-stimulated androgen-independent cell lines DU 145 and PC-3 in vitro, supporting the potential of AZA1 for use in prostate cancer." (PMID 24040362, 2013).
prostate carcinoma (continued). "The BAD protein represents a switch integrating the antiapoptotic effects of multiple pathways in prostate cancer cells, thus expression of a nonphosphorylatable mutant S112A-BAD reduces the survival effects of growth factors such as EGF in prostate cancer cells." (PMID 24040362, 2013). "To analyze whether AZA1 can also reduce cellular proliferation in EGF stimulated cells, we treated EGF-stimulated prostate cancer cells with AZA1." (PMID 24040362, 2013). "In addition, EGF is reported to activate NF-κB in several cancers including human epidermal carcinoma cell lines, breast and prostate cancer cells." (PMID 24340014, 2013). "Similarly, we observed a high ratio of F-actin to G-actin in all three investigated prostate cancer cell lines, which was further increased by EGF stimulation." (PMID 24040362, 2013). "It has also been reported that EGF may increase metastatic potential of prostate cancer by up regulation of SCN9A." (PMID 21314958, 2011). "Among the growth-factor families involved in prostate-cancer progression, Transforming Growth Factor-beta (TGFβ), Fibroblast Growth Factors (FGFs), Epidermal Growth Factor (EGF) and heparin affin regulatory peptide (HARP) were reported to play a prominent role." (PMID 21624116, 2011). "This receptor downregulates the stimulatory effect of EGF on the growth of prostate cancer cells." (PMID 22013484, 2011). "In addition, more recently, it has been reported that loss of POB1 expression in prostate cancer cells results in deregulation of growth factor signaling, while an increase of POB1 expression has been correlated with silencing of EGF signaling." (PMID 18647389, 2008). "Moreover, POB1 isoform 2 down-regulation has been observed during progression of prostate cancer from androgen to EGF dependency." (PMID 18647389, 2008). "The results together, indicated that STAT3 could be a targeted critical element in the EGF-mediated cell migration and invasion of prostate carcinoma cells." (PMID 16804520, 2006). "Bone-derived EGF may contribute to prostate cancer metastasis." (PMID 37375411, 2023). "Taken together, identifying the role of YB-1 and exploring the correlation between the EGF regulation and relevant kinase pathways in the progression of prostate cancer may clarify the prostate biology as well as aiding the development of novel therapeutics for that disease." (PMID 34696665, 2021). "Finally, to determine whether our findings could be relevant to prostate cancer, we decided to examine EGF and IGFs expression in human samples." (PMID 32385236, 2020). "The epidermal growth factor (EGF)/Src tyrosine kinase pathway also contributes to the induction of EMT in TMPRSS2:ERG positive prostate cancers, and Kao and colleagues demonstrated that this interaction may be mediated by downregulation of miR-30, which normally suppresses ERG expression." (PMID 25496077, 2014). "Importantly, as shown in prostate cancer, a combination of EGF and androgen further induced AR transcriptional activity in all the three bladder cancer lines tested and the AR antagonist HF completely abolished AR transactivation induced by EGF, androgen, or both at least in UMUC3." (PMID 22922989, 2012). "However, it was shown that the effect of EGF on AR transcription might be almost negligible compared to the induction by androgens in prostate cancer." (PMID 22922989, 2012). "Furthermore, in prostate cancer cells, EGF treatment can promote tumour cell motility and invasion." (PMID 21326240, 2011). "We identified that fetal bovine serum, some growth factors (epidermal growth factor, androgen, insulin-like growth factor-I, and hepatocyte growth factor) and cytokines (TNFα and interleukin-1beta) induced midkine expression in a human prostate cancer cell line LNCaP cells." (PMID 18275606, 2008).
prostate carcinoma (continued). "For example, EGF, transforming growth factor α, insulin-like growth factor 1, interleukin 6, keratinocyte growth factor, and other fibroblast growth factor family members are expressed in advanced prostate cancers and are believed to be important in fueling androgen-independent growth." (PMID 17384772, 2007). "The most upregulated gene in SHP2R138Q-expressing cells, considering both SHP2-driven effects and EGF-induced effects, was COBLL1, which is involved in the oncogenesis of prostate cancer and chronic lymphocytic leukemia." (PMID 40631144, 2025). "In prostate cancer, FBXW2 facilitates epidermal growth factor receptor ubiquitination and degradation, thereby inhibiting EGF-induced growth and metastasis." (PMID 40225854, 2025). "STAP-2 increases EGFR phosphorylation in response to EGF and upregulates EGFR signaling in the prostate cancer cell line DU145." (PMID 38461189, 2024). "Quercetin can also impair epidermal growth factor (EGF)-induced EMT and hinder the invasiveness of prostate cancer cells through PI3K/Akt signaling pathway." (PMID 38990915, 2024). "PTHrP gene expression is upregulated via a transcriptional mechanism by epidermal growth factor (EGF), which is secreted by prostate cancer cells." (PMID 39200986, 2024). "VEGF-A and TGF-β promote Snail nuclear localization in prostate cancer cells, while TGF-β and EGF induce EMT in prostate cancer cells, leading to their distinct metastatic potential." (PMID 38398019, 2024). "With the hope of being able to aid the development of novel therapeutics, this study aimed at characterizing the EGF regulation in YB-1 and CXCL14 expression and their relevant kinase pathways in prostate cancer cells and tissues." (PMID 34696665, 2021). "Similar results for Pyk2 and FAK have been observed in different cell types (hemopoietic cancer cells, ovarian cancer cells, smooth vascular cells, and prostate cancer cells) following treatment with SDF-1α, IL-6, EGF, IL-8, and PDGFβ." (PMID 34944779, 2021). "The possible links between EGF-mediated YB-1 and CXCL14 as well as the functions of critical kinase pathways in the progression of prostate cancer have remained unexplored." (PMID 34696665, 2021). "In conclusion, our data reveal the functional relationship between YB-1 and CXCL14 in EGF mediated ERK signaling, and YB-1 expression is a significant prognostic marker to predict prostate cancer." (PMID 34696665, 2021). "Many studies have confirmed that EGF/EGFR signaling is one important growth factor signaling involved in the regulation, proliferation, and survival of prostate cancer." (PMID 34069970, 2021). "Previous studies have shown that EGF activates the PI3K/AKT pathway and promotes leucine uptake by prostate cancer cells, thereby promoting tumor development." (PMID 33407468, 2021). "In prostate cancer cells and xenografts, the combination of increased HGF (hepatocyte growth factor) and EGF (epidermal growth factor) production, combined with the acidic extracellular pH, triggers signaling events that elevate the expression of Arl8b." (PMID 33718382, 2021). "We found that the supernatant of PC3 prostate cancer cells promoted the expression of CD206, VEGFA and EGF in THP‐1 indicating the polarization of TAM." (PMID 32469149, 2020). "Growth factors and their receptors are commonly increased in a variety of cancers, with expression of epidermal growth factor (EGF) and its receptor (EGFR) significantly increased in prostate cancer." (PMID 31345230, 2019). "A close link between SERCA inhibition by thapsigargin and the ER calcium pool content depends on the epidermal growth factor (EGF) concentration, as was observed in LNCaP prostate cancer cells." (PMID 31226817, 2019).
prostate carcinoma (continued). "UBASH3B has been detected in prostate cancer cell lines and UBASH3B knockdown can decrease EGF-induced invasion and form tumor spheres in PC3 and DU145 cells." (PMID 32010618, 2019). "By using the prostate cancer cell line, PC3 cells, we also found that EGF treatment indeed induced mitochondrial elongation (P < 0.0001)." (PMID 26497368, 2015). "In prostatic cancer cells Byles and colleagues observed Sirt1 to modulate EMT upon EGF signalling via the induction of the transcription factor ZEB1." (PMID 24088390, 2013). "The very signaling pathways now recognized as being cholesterol-dependent: AR, TGFβ, EGF, MAPK/ERK, AP-1, and AKT, are well characterized as prostate cancer relevant." (PMID 23919967, 2013). "The human prostate expresses functionally active CB1 receptors, and anandamide reduces the rate of epidermal growth factor- (EGF) and prolactin-stimulated growth of human prostate cancer cell lines in a manner involving activation of CB1 receptors." (PMID 23755281, 2013). "To achieve selectively into cancer cells, we engineered a fusion protein epidermal growth factor (EGF)-SubA, combining EGF with SubA, which demonstrated significant inhibition of human breast and prostate cancer cells in vitro and in vivo." (PMID 23284962, 2012). "Several ways to induce EMT in prostate cancer cells have been described, including overexpression of CAV1 and ID1 or MMP14 in LNCaP cells, EGF treatment of DU145 cells, depletion of PDEF or BMP7 treatment of PC3 cells." (PMID 18852876, 2008). "To define the molecular mechanisms involved in the regulation of EGFR expression by EGF and TGF-α we studied three human prostate cancer cell lines, androgen-responsive (LNCaP) and -unresponsive (DU145 and PC3)." (PMID 10360641, 1999). "We measured immunoreactive EGF and TGF alpha in prostate tissue extracts obtained from 19 patients with benign prostatic hyperplasia (BPH) and 19 with cancer of the prostate (CaP)." (PMID 7678977, 1993). "The present study was undertaken to compare the relationship between response to exogenous epidermal growth factor (EGF) and the expression of the EGF-receptor (EGF-R) in an androgen sensitive (LNCaP) and insensitive (DU145) prostate cancer cell line." (PMID 1739613, 1992). "Thus, the current study supports the competent cytotoxic effect of CDRI-08 against androgen-independent prostate cancer cell lines, PC3, targeting the PI3K/Akt pathway, in combination with CYP17A1 inhibitor, AA, even in the presence of EGF and DHT." (PMID 40809182, 2025). "EGF-PE24mut showed high and specific cytotoxicity in the EGFR-expressing prostate cancer cells." (PMID 37859824, 2023). "The EGF (epidermal growth factor)-stimulated growth of cell lines, such as DU-145 and LNCaP prostatic cancer, were inhibited by biochanin-A without affecting its autophosphorylation." (PMID 38106650, 2023). "EMT is a common phenomenon in prostate cancer, which might be induced by many tiggers (endocrine therapy), and there were interactions among various signaling pathways (Wnt/β-Catenin, TGF-β, EGF, PDGF)." (PMID 37726835, 2023). "In prostate cancer, ET-1 also promotes cancer cell proliferation and enhances the mitogenic effects of other growth factors including IGF-1, platelet-derived growth factor (PDGF), and epidermal growth factor (EGF)." (PMID 36230816, 2022). "Finally, EGF was found to be a key factor upstream of AKT/δ-catenin/p21 for promoting proliferation and metastasis in prostate cancer." (PMID 34069970, 2021). "Our study also showed that EGF regulate CXCL14 transcription, and that CXCL14 is inversely correlated with YB-1 in prostate cancer cells, suggesting a possible mechanism of YB-1 regulation in the cell cycle and in apoptosis in prostate cancer." (PMID 34696665, 2021). "Consistent with those previous findings, our present study proved that an EGF-dependent increase of phospho ERK and phospho YB-1 could modulate the progression of prostate cancer." (PMID 34696665, 2021).